CCDC74A (coiled-coil domain containing 74A)
Synonyms: FLJ40345
Tractability: No criterion of Open Targets' tractability assessment is met for any kind of drug.
Gene: Protein-coding gene on chromosome 2 (131,527,675 to 131,533,666, forward strand). Ensembl gene ENSG00000163040.
Subcellular location (Human Protein Atlas): Basal body; Centrosome; Cytosol; Nucleoplasm
Gene Ontology:
Molecular function: protein binding
Genetic constraint (gnomAD): Loss-of-function variants: 38 observed, 36.47 expected, observed/expected ratio (o/e) 1.04, 90% interval 0.8 to 1.37. The upper end of that interval is the gene's LOEUF score, 1.37, which puts it in group 5 of 6, group 1 being the genes least tolerant of losing a copy. Missense variants: 340 observed, 373.7 expected, observed/expected ratio (o/e) 0.91, 90% interval 0.83 to 1. Synonymous variants: 134 observed, 149.71 expected, observed/expected ratio (o/e) 0.9, 90% interval 0.78 to 1.03.
Homologues: Orthologues: chimpanzee CCDC74B (98% identical), mouse Ccdc74a (69% identical), rat Ccdc74a (68% identical). Paralogues in human: CCDC74B (98% identical).
Diseases named in the same sentence as CCDC74A in open-access papers:
CCDC74A is named in the same sentence as 3 diseases in open-access papers, as found by Europe PMC text mining. Sharing a sentence is not in itself a finding about the gene and the disease. The quoted sentences say what the papers report.
prostate carcinoma (1 paper, 2023). A carcinoma that arises from epithelial cells of the prostate gland. "GAPDH could enhance the transcriptional activity of AR in prostate cancer cells, and PPIB could regulate cell-cycle related genes including CCDC74A which further promotes cell proliferation." (PMID 37729607, 2023).
CCDC74A also shares sentences with these, for which no sentence is quoted: cancer (1 paper); tumor (1).